IFNG (interferon gamma)
Diseases named in the same sentence as IFNG in open-access papers (continued):
Sharing a sentence is not in itself a finding about the gene and the disease.
infection (continued). "The level of IFNγ was similar after all infections; IL-1β was the highest in PEC after cps1-1 and in spleen after ME49; IL-17A was increased after cps1-1 and ME49 in PEC; IL-10 was increased after RH and ME49 in spleen." (PMID 27721814, 2016). "Four week following aerosol infection, IL-21R−/− T cells are reduced in the blood and lungs relative to WT T cells, and produce less IFNγ and TNF, similar to experiments performed with IL-12R−/− CD8+ T cells." (PMID 27819295, 2016). "While no changes in tissue integrity were observed after 1 week of infection in both groups (Fig 2A1–2A3 and 2B1–2B3), the two IFNγ-/- mice displayed massive oedema formation and tissue necrosis after 5 weeks of infection (Fig 2B5, 2B4 and 2B6, respectively)." (PMID 26863011, 2016). "We found that the ability of NK cells to exacerbate infection was independent from their production of IFNγ and instead due to subsequent production of the anti-inflammatory cytokine IL-10." (PMID 27295349, 2016). "In murine models of infection, Lm elicits a robust innate immune response that is characterized by IFNγ production by activated NK cells." (PMID 27295349, 2016). "In contrast, more AFB were detected in both IFNγ-/- mice 5 weeks after infection (Fig 3C3 and 3C4), as compared to the two WT controls (Fig 3C1 and 3C2), which again corresponded with the results of the qPCR analysis." (PMID 26863011, 2016). "At 2 days after infection, IFNγ+ NK cells predominated but by day 3 the number of IFNγ producing NK and T cells were similar." (PMID 27300652, 2016). "The antigen distribution of TMUV and GPV during infection in geese was coincident with the CD8+ T cell distribution, which was also associated with the high production of IFNγ and proinflammatory cytokine (IL1β and IL6) in virus-preferable tissues." (PMID 27150912, 2016). "The skin gDT-II cells were found to rapidly produce IFNγ on secondary infection with HSV, with the highest response between 24 and 48 h after challenge." (PMID 27160938, 2016). "Such infections include the apicomplexan parasite Toxoplasma gondii, in which case IFNγ drives effector mechanisms to eliminate the fast replicating acute phase tachyzoite stage." (PMID 26874079, 2016). "Lung IFNγ levels were increased inM-TNFR1 KO mice already at 3 weeks post infection, and further elevated in micedeficient for TNFR1 completely or only on myeloid cells at 4 to 5 weeks afterM." (PMID 26931771, 2016). "These include IL-12/IFNγ axis, IL-15–independent NK cell infection responses, costimulation, and T-bet role in NK cell dependent protection." (PMID 26915066, 2016). "Consistent with this, we show that the majority of the skin CD4+ T cells that produce the antiviral cytokine IFNγ upon secondary infection with HSV are localized to hair follicles." (PMID 27160938, 2016). "In models of infection and inflammation, IFNγ activates HSCs to differentiate and impairs their ability to self-renew, ultimately leading to HSC exhaustion." (PMID 27621733, 2016). "In IFNγ-treated cells, virus production of Ad5-WT and Ad5-mut1 gradually increased from 0 to 30 days post-infection." (PMID 26809031, 2016). "If IFNγ contributed to protection of NSPCs in the CD46+ model, then we would predict greater apoptosis in CD46+/IFNγ-KO mice during infection." (PMID 27178303, 2016). "We therefore quantified the number of virus-specific CD8+T cells and their ability to produce intracellular cytokine IFNγ and/or TNFα day 7 after infection." (PMID 27245318, 2016). "IFNγ-producing γδ T cells also peaked 3 to 7 days post-infection, but represented a minor population when compared to IFNγ-producing NK cells at similar time points." (PMID 25747674, 2015). "In WT mice, when the concentrations of IFNγ and TNFα increase during clearance of infection, the concurrent induction of IL-4 and IL-6 thus appears to protect the mitochondrial function of the colonic epithelium from further damage." (PMID 26481427, 2015).
infection (continued). "As IFNγ and TNFα levels increase during clearance of infection, the concomitant increase in IL-4 and IL-6 protects mitochondrial function." (PMID 26481427, 2015). "Both human γδ T-cell subsets are highly prone to secrete IFNγ, but IL-17 can be induced in highly inflammatory conditions triggered by infections or tumors." (PMID 25674089, 2015). "IFNγ is the major pro-inflammatory cytokine driving multiple cellular defense mechanisms during both the acute and chronic phases of infection." (PMID 26473595, 2015). "By 5 days post-infection mice exhibit a moderately enlarged spleen, and higher systemic levels of the macrophage-activating cytokines, IFNγ and TNF15." (PMID 25944649, 2015). "In the context of systemic disease, however, IFNγ-producing Th1 cells appear essential early in the course of infection." (PMID 26539822, 2015). "Administration of anti-CCR2 or anti-Gr-1 mAb during an ongoing PbTg infection also resulted in reduced IFNγ levels in the brains, which was significant in the case of anti-Gr-1, demonstrating again a strong effect of this clone." (PMID 25884830, 2015). "The amounts of cytokines, Tnfα Interleukin 6 (Il6) and Ifnγ in the sera increased significantly by day 4 post infection in both C57BL/6 and Nos2-/- mice." (PMID 26029930, 2015). "This coincided with reduced local and systemic IFNγ levels, confirming that these cells are the major IFNγ producers during early infection." (PMID 26070118, 2015). "In cotton rat model of Human Parainfluenza 3 laryngotracheitis IFN-γ mRNA expression in laryngeal tissues was increased by infection and corticosteroid treatment, which reduced the extent of lesions, led to a measurable reduction of IFNγ expression." (PMID 25722655, 2015). "In vitro infection further increased the generation of NO2−, and IL-4 alleviated both the NO2− generation-induced by the bacteria alone (p < 0.01) and by the combined actions of infection, IFNγ and TNFα (p < 0.01)." (PMID 26481427, 2015). "Neutralizing IL-33 during primary infection in neonates resulted in significant reductions in Th2 and multifunctional Th (mTh; IFNγ+, IL-4+) cells upon reinfection (α-IL-33+NRR)." (PMID 26473724, 2015). "Three weeks post infection, neutropenic mice had a higher fraction of intracellular IFNγ+ CD4+ T cells in the dLN." (PMID 26020515, 2015). "IFNγ and IL-12 mRNA were upregulated at all time points, whereas TNFα and IL-4 upregulation started at day 14 and IL-6 mRNA only increased at day 19 post infection." (PMID 26481427, 2015). "First, during the acute phase of infection, on d7, when parasitaemia is growing but relatively low, IFNγ was the cytokine with the highest expression levels, followed by IL6 and IL12." (PMID 25890318, 2015). "To approach the effects of IFNγ on astrocytes submitted to T. cruzi infection we established an in vitro infection model of monotypic primary astrocyte cell cultures." (PMID 25695249, 2015). "Infection with C. rodentium resulted in an increase in immunostaining intensity for 3-Nitrotyrosine (3-NT), a marker for oxidative damage, in both infected WT and IFNγ−/− mice at all time points post-infection (p < 0.05–0.0001)." (PMID 26481427, 2015). "The immunosuppressive activity of IL-10 is required for maintaining healthy immunity during infection, and has pleiotropic effects on many inflammatory mediators, notably through suppressing a number of innate and adaptive cytokines including IFNγ." (PMID 26252010, 2015). "Similar trends were observed in mice treated with IFNγ 2 hours following EBOV GP/rVSV infection, but splenic virus loads were higher in these mice, suggesting that some virus had trafficked to the spleen by 2 hours following inoculation." (PMID 26562011, 2015). "The aim of this study was to evaluate the effect of the HPIV3 infection on cultured human nasal epithelial cells (HNECs) and the release of interferon gamma and other cytokines." (PMID 25722655, 2015).
infection (continued). "Subsequently, APECs from uninfected mice were isolated, Ifnγ was added 2 h post infection and cells were imaged at 24 h post Ifnγ treatment." (PMID 26029930, 2015). "We therefore determined the relative magnitude of responses to all the epitopes recognized in each subject at time-points over the first year of infection using IFNγ ELISpot assays." (PMID 25569444, 2015). "Similar to the MDM cultures, M-CSF-treated cells were permissive for virus, whereas the addition of IFNγ prevented infection of these cells." (PMID 26562011, 2015). "Surprisingly, in vitro experiments revealed that pretreatment with IFNγ promoted the infection of astrocytes by T. cruzi increasing uptake and proliferation of intracellular forms, despite inducing increased production of nitric oxide (NO)." (PMID 25695249, 2015). "The cross-reactive T cells during acute secondary infection have an altered cytokine responses consisting of low interferon gamma (IFN-γ) and high tumor necrosis factor alpha (TNF-α)." (PMID 26065421, 2015). "In line with the higher IFNγ levels observed in neutropenic mice, the frequency and number of infected cells were lower at 8 weeks post infection in these mice in the ear dermis." (PMID 26020515, 2015). "This is further supported by the observation that in the WT mice, the mitochondrial respiratory chain remained impaired even at day 19 post infection, when the pathogen burden had subsided, but the expression of TNFα and IFNγ remained elevated." (PMID 26481427, 2015). "This indicates that IFNγ production occurs very early in infection, even before macrophage activation." (PMID 26070118, 2015). "Chronic granulomatous patients receive IFNγ three times weekly to prevent infections, which can serve as life-long protective treatment in these patients." (PMID 26562011, 2015). "As a control for these studies, we also evaluated the ability of IFNγ to protect against wild-type VSV infection." (PMID 26562011, 2015). "Previous research on African trypanosome infections has established an important role for IFNγ during the onset of infection." (PMID 26070118, 2015). "Overall these studies suggest that clearance of Ct infection requires an appropriate acute Th1 response with IFNγ and CD8+ T cells." (PMID 26424969, 2015). "NK cells are responsible for the production of the major portion of IFNγ during early phases of the infection." (PMID 26296209, 2015). "Consistently with the cytometry and the immunofluorescence data, the transcription of Ifnγ, Il17, Tnf and Nos2 was similar in both groups at day 30 post-infection." (PMID 26135889, 2015). "Infection with H. pylori significantly upregulated gastric expression of pro-inflammatory cytokines including: interferon gamma (IFNγ) (p<0.0001)., tumor necrosis factor alpha (TNFα), (p<0.0001) and Interleukin 1 beta (IL1β) (p<0.05)." (PMID 26575645, 2015). "Mice given 10 μg of IFNγ by i.m. injection 24 hours prior to EBOV GP/rVSV infection significantly protected against lethal challenge." (PMID 26562011, 2015). "Combining treatments of TNFα and IFNγ, in analogy with the in vivo cytokine expression during day 14 and 19 post infection, further decreased complex I and IV activity (−58% and −52%, P < 0.001)." (PMID 26481427, 2015). "In the liver on day 7 after infection a transient increase of IFNγ-producing γδ T cells was observed." (PMID 25658831, 2015). "This difference is probably due to the observed and already described low number of T cells in the nude mice, leading to a compromised IFNγ production, inflammation in the site of infection and parasite clearance." (PMID 25692783, 2015). "Again, these results are consistent with the idea that IFNγ plays a beneficial role in the heart tissue injury during chagasic infection." (PMID 25617628, 2015). "Astrocytes were pretreated with IFNγ for 2 hours before infection with T. cruzi and parasite entry was measured 4 hours after infection." (PMID 25695249, 2015).
infection (continued). "Using a murine model of recurrent S. aureus peritonitis, we demonstrated that prior exposure to S. aureus enhanced IFNγ responses upon subsequent infection, while adoptive transfer of S. aureus antigen-specific Th1 cells was protective in naïve mice." (PMID 26539822, 2015). "GITR triggering also boosted the helper function of virus-specific CD4 T cells already early in the infection, as was evidenced by increased IL-2 and IFNγ production, and more expression of CD40L and T-bet." (PMID 25738498, 2015). "In summary, our work suggests a protective function of NK cells in modulating IFNγ levels in response to an oral Y. pseudotuberculosis infection, leading to clearance of the bacteria from the mLNs during the early phases of infection." (PMID 26296209, 2015). "Infection clearance in resistant mice requires Th1 adaptive responses mediated by the IFNγ-stimulated chemokines CXCL9, CXCL10, and CXCL11 acting in a CXCR3 dependent manner." (PMID 25643352, 2015). "At the peak of clinical signs, 7 days post infection, the calves in study 2 also demonstrated an increase of IFNγ and minimal amounts of IL-4 in BAL supernatant, which agrees with previously reported responses to primary BRSV infection in calves." (PMID 25890239, 2015). "While the authors attributed these findings to increased T cell homing to site of infection, an alternative or additional interpretation, given our current results, is the attendant increase in innate defense mediated by IFNγ-stimulated CXCL9 release." (PMID 25643352, 2015). "IFNγ is a pleiotropic cytokine secreted by T-helper-1 (Th1) cells, promoting both innate and adaptive responses to infection within the host." (PMID 26345454, 2015). "Murine IFNγ reduced EBOV infection in a dose-dependent manner with 20 pg/mL of IFNγ inhibiting more than 70% of infection and 2 ng/mL providing greater than 95% protection." (PMID 26562011, 2015). "For example, low-level expression of CXCL9 was described in IFNγ-/- mice following infection with vaccinia virus." (PMID 25643352, 2015). "Therefore, here we have questioned whether in vivo parasite persistence was associated with IFNγ expression and which effects IFNγ has on primary astrocyte cell cultures infected with the Colombian T. cruzi strain, evaluating susceptibility to infection and cell activation." (PMID 25695249, 2015). "Il-18-/- mice quickly succumb to the infection and showed higher bacterial burden in organs and lower level of IFNγ in BALF and serum compared to wild type C57BL/6J mice." (PMID 25768794, 2015). "Previous work by our laboratory found that depletion of IFNγ-producing NK1.1+ CD3- cells reduced CXCL9 levels in the C. rodentium-infected gut, leading to increased host susceptibility to infection." (PMID 25643352, 2015). "The presence of both IL-4 and IL-6 during the clearance phase of infection, when TNFα and IFNγ levels are exceedingly high, protects the colonic epithelial surface against more detrimental damage." (PMID 26481427, 2015). "As infection progressed, the ratio of IL-13 to IFNγ expanded such that by 7 dpi, IL-13 was significantly greater than IFNγ in RSV-infected neonates." (PMID 26438053, 2015). "Neutralizing antibodies against IFNγ or IL-17 or isotype control antibodies were given to the animals before and during the time course of the infection." (PMID 25658831, 2015). "Using mouse-adapted Ebola virus, we found that murine interferon gamma administered 24 hours before or after infection robustly protects lethally-challenged mice and reduces morbidity and serum viral titers." (PMID 26562011, 2015). "We also evaluated the ability of parasite isolates to establish an infection in classically activated macrophages (IFNγ plus LPS;)." (PMID 25695070, 2015). "In contrast, macrophages from BALB/c or C57BL/6 IFNAR-/- mice were highly permissive to EBOV GP/rVSV and IFNγ treatment of these cells profoundly decreased infection in a dose dependent manner." (PMID 26562011, 2015).
infection (continued). "In these studies, six-day M-CSF matured human monocyte derived macrophages (hMDMs) were treated for 24 hours prior to infection with TNFα and/or IFNγ." (PMID 26562011, 2015). "At the initial phase of infection, monocytes are effectively recruited to the inflammation site, being stimulated by cytokines such as IFNγ and IL-4 to differentiate into macrophages." (PMID 26135738, 2015). "During MHV68 infection, M1 plays an important role in suppressing viral reactivation from latently infected peritoneal macrophages, through activation and expansion of IFNγ producing Vβ4+ CD8+ T cells." (PMID 26317335, 2015). "Here we demonstrated that parasite persisted in the presence of IFNγ mRNA expression and production in the CNS in acute and chronic T. cruzi phases of infection." (PMID 25695249, 2015). "The interferon-gamma (IFN-γ)-producing anti-viral Type 1 T helper cell (Th1) response against the HBV core has been found to be stronger in patients with resolved infection even several years after infection." (PMID 26263973, 2015). "In order to evaluate the role of NKT cells in the present model, we performed cytokine staining (IFNγ, TNFα and IL-4) three days post infection." (PMID 26296209, 2015). "Both infection and TNFα, individually and combined with IFNγ, decreased complex I and IV enzyme levels and mitochondrial function." (PMID 26481427, 2015). "To elucidate the role of the cytokine environment versus the direct actions of C. rodentium in vivo, we studied IFNγ−/− mice, as IFNγ increased early in infection, concomitantly with the mitochondrial dysfunction (in contrast to TNFα)." (PMID 26481427, 2015). "In the primate and human brain, QUIN levels are strongly induced by interferon gamma (IFN-γ), a cytokine that is upregulated during infection and inflammation and following hypoxia-ischemia." (PMID 26025142, 2015). "AVP vaccination was found to result in a polarized IFNγ CD4+ T cell response, while the individuals exposed to B. anthracis by natural infection mounted a broader cytokine response encompassing IFNγ, IL-5, −9, −10, −13, −17, and −22." (PMID 26075052, 2015). "It is generally accepted that IFNγ plays a key role in early stages of infection and CD8 and CD4 T cells have been indirectly suggested to be the sources of IFNγ during T. b. brucei infection." (PMID 26070118, 2015). "Cytokine mRNA quantification showed increased levels of IFNγ, TNFα, IL-4, IL-6, and IL-12 during infection." (PMID 26481427, 2015). "The anti-TNF antibody Infliximab completely abrogated IFNγ effects on astrocyte infection by T. cruzi." (PMID 25695249, 2015). "The cytokine environment during the course of infection was different in IFNγ−/− compared to WT mice, mainly with regards to that IL-4 and IL-6 were upregulated already by day 10 post infection (3-fold vs 20-fold)." (PMID 26481427, 2015). "We note that IL-12 and IFNγ (a Th1 cytokine response), and IL-10, IL-4, IL-13 or IL-5 (Th2 cytokine response) were either down-regulated during the latter phase of infection or remained unchanged." (PMID 25719526, 2015). "Overall, our studies provide novel mechanistic insights into the roles of Nos2 in mediating morphology, motility and aggregation behavior of APECs upon Ifnγ stimulation and in response to infection with S. Typhimurium." (PMID 26029930, 2015). "IFNγ treatment protected against VSV only when given prior to infection, whereas post-challenge treatment appeared somewhat more efficacious against EBOV than pre-challenge treatment." (PMID 26562011, 2015). "As early as six hours following in vitro infection, Ebola virus RNA levels in interferon gamma-treated macrophages were lower than in infected, untreated cells." (PMID 26562011, 2015). "In this work we show that F. hepatica glycoconjugates are involved in the induction of high levels of IL-10 and IL-4 as well as in the reduction of IFNγ production by splenocytes during infection." (PMID 26720149, 2015).